RGS1 (regulator of G protein signaling 1)
Diseases named in the same sentence as RGS1 in open-access papers (continued):
Sharing a sentence is not in itself a finding about the gene and the disease.
autoimmune thyroid disease (1 paper, 2025). Inflammatory disease of the thyroid gland due to autoimmune responses leading to lymphocytic infiltration of the gland. "Increased IL-10 expression has been reported in autoimmune thyroid diseases, suggesting that anti-inflammatory responses may occur simultaneously via IL10RB, DUSP1, DUSP2, and RGS1 in GD." (PMID 40710355, 2025).
brucellosis (1 paper, 2024). Brucellosis is a bacterial infection that spreads from animals to people via unpasteurized dairy products or by exposure to contaminated animal products or infected animals. "Interestingly, a series of commonly upregulated genes were identified in brucellosis patients, with seven genes/transcription factors (RGS1, DUSP1, FOS, PPP1R15A, TNFAIP3, HLA‐E, and ZFP36) being the most frequent (nine times among nine clusters)." (PMID 39135683, 2024).
cervical squamous cell carcinoma (1 paper, 2022). A squamous cell carcinoma arising from the cervical epithelium. "First, we detected RGS1 mRNA expression in 10 cervical adenocarcinoma carcinoma tissues, 10 cervical squamous cell carcinoma tissues, and 10 normal cervical tissues." (PMID 35879796, 2022). "Next, we determined the level of RGS1 protein expression in 20 cervical adenocarcinoma carcinoma tissues, 20 cervical squamous cell carcinoma tissues, and 20 normal cervical tissues by immunohistochemistry." (PMID 35879796, 2022). "Our study found that RGS1 protein expression was higher in HPV-E6-positive patients than HPV-E6-negative patients in both cervical squamous cell carcinoma and adenocarcinoma." (PMID 35879796, 2022).
childhood asthma (1 paper, 2022). "Results showed that the mRNA expression levels of CD3D, CD3G, HLA-DMB, CD69, RGS1, and CIITA were significantly upregulated in childhood asthma patients compared with healthy controls, consistent with bioinformatics analysis." (PMID 36118895, 2022). "Results showed that the mRNA levels of CD3D, CD3G, HLA-DMB, CD69, RGS1, and CIITA were significantly upregulated in childhood asthma patients compared with the control individuals." (PMID 36118895, 2022). "Based on qRT-PCR validation, CD3D, CD3G, HLA-DMB, CD69, RGS1, and CIITA were shown to be upregulated in childhood asthma patients." (PMID 36118895, 2022).
chronic kidney disease (1 paper, 2016). Impairment of the renal function secondary to chronic kidney damage persisting for three or more months. "Of special note, rs6428106 (5.3 kb 3′ of RGS1) was suggested to be associated with chronic kidney disease among participants of African ancestry." (PMID 27804980, 2016).
clear cell ovarian cancer (1 paper, 2013). "The most statistically significant association was between survival following clear cell ovarian cancer (N = 217) and minor alleles at an uncommon intronic SNP in the regulator of G-protein signaling 1 (RGS1), suggesting an almost three-fold increased risk of death (p = 2.7×10−5)." (PMID 23382860, 2013).
cognitive decline (1 paper, 2025). "Additionally, RGS1 and DUSP1 are involved in inflammation and immune signaling, which are increasingly recognized as key contributors to cognitive decline." (PMID 40624693, 2025).
Cognitive impairment (1 paper, 2025). Abnormal cognition is characterized by deficits in thinking, reasoning, or remembering. "RGS1 and DUSP1 showed differential expression across all three cognitive impairments." (PMID 40624693, 2025).
colorectal tumor (1 paper, 2015). "RGS1 gene expression was found to be up-regulated both in normal and colorectal tumor tissue upon resection." (PMID 26222051, 2015).
cutaneous melanoma (1 paper, 2020). A primary melanoma arising from atypical melanocytes in the skin. "In OSskcm, KIF20A and RGS1 were found to be strongly associated with cutaneous melanoma prognosis." (PMID 32467670, 2020).
frontotemporal dementia (1 paper, 2023). Frontotemporal dementia (FTD) comprises a group of neurodegenerative disorders, characterized by progressive changes in behavior, executive dysfunction and language impairment, as a result of degeneration of the medial prefrontal and frontoinsular cortices. "Decorin (DCN) and regulator of G protein signaling 1 (RGS1) were screened as diagnostic biomarkers in distinguishing AD from frontotemporal dementia and Huntingdon’s disease of AD." (PMID 37234685, 2023). "DCN and RGS1 associated with the immune response may be useful biomarkers for diagnosing AD and distinguishing the disease from frontotemporal dementia and Huntingdon’s disease." (PMID 37234685, 2023).
fungal infection (1 paper, 2022). "However, the negative regulatory role of RGS1 stimulated by STAT1 during the immune response against fungal infection remains to be further studied." (PMID 36225936, 2022).
hepatocellular carcinoma (1 paper, 2023). A malignant tumor that arises from hepatocytes. "For instance, one study reveals that RGS1 is elevated in hepatocellular carcinoma at the initiation stage and tumourigenic stage compared with controls." (PMID 38081176, 2023).
IgA Nephropathy (1 paper, 2016). "We observed novel associations of RGS1 and RASGRP1 variants in IgA Nephropathy." (PMID 27804980, 2016). "In conclusion, we observed novel associations of RGS1 and RASGRP1 variants in IgA Nephropathy." (PMID 27804980, 2016).
Insulin resistance (1 paper, 2022). Increased resistance towards insulin, that is, diminished effectiveness of insulin in reducing blood glucose levels. "The two reported studies on the involvement of RGS1 in insulin resistance are superficial." (PMID 36497154, 2022). "The findings of these two studies are generally consistent, indicating an upregulation of RGS1 expression in the WAT of mice with obesity, insulin resistance, and dyslipidemia." (PMID 36497154, 2022).
intestinal infection (1 paper, 2023). "Genetic deletion of Rgs1 in antigen-specific CD8+ T cells significantly impaired their accumulation at the site of intestinal infection." (PMID 37153600, 2023). "Here we report that Rgs1 expression is readily induced in naïve OT-I T cells in vivo following intestinal infection with Listeria monocytogenes-OVA." (PMID 37153600, 2023). "After intestinal infection with Listeria monocytogenes-OVA, however, OT-I Rgs1+/+ T cells outnumbered the co-transferred OT-I Rgs1-/- T cells in the small intestinal mucosa already early after infection." (PMID 37153600, 2023).
ischemia (1 paper, 2015). A hypoperfusion of the BLOOD through an organ or tissue caused by a PATHOLOGIC CONSTRICTION or obstruction of its BLOOD VESSELS, or an absence of BLOOD CIRCULATION. "The results presented here demonstrate a link between the expression of RGS1 and the post-operative effects of ischemia." (PMID 26222051, 2015).
leukemia (1 paper, 2024). A malignant (clonal) hematologic disorder, involving hematopoietic stem cells and characterized by the presence of primitive or atypical myeloid or lymphoid cells in the bone marrow and the blood. "The concept whereby inhibition of the CXCL12‐CXCR4 axis by RGS1 contributes to leukemogenesis might appear to contradict recent findings showing that leukemia cells use the CXCL12‐CXCR4 axis to access and reside in a bone marrow microenvironment that is expected to favor their growth and survival." (PMID 39015025, 2024).
liver cancer (1 paper, 2021). An epithelial or non-epithelial malignant neoplasm that arises from the liver. "Additionally, we performed IHC verification to quantify the protein expression of RGS1 using the local clinical samples of liver cancer and normal tissues, similarly, RGS1 protein displayed stronger staining in hepatocarcinoma, in line with the statistical result (p = 7.1e−5)." (PMID 34956194, 2021). "Apart from that, the protein level of RGS1 in HPA database showed the immunohistochemical (IHC) staining of RGS1 was negative staining in normal tissues and positive in liver cancer tissues, demonstrating that RGS1 was significantly expressed in cancer tissues than in normal liver tissues." (PMID 34956194, 2021).
Moyamoya disease (1 paper, 2025). Moyamoya disease (MMD) is a rare intracranial arteriopathy involving progressive stenosis of the cerebral vasculature located at the base of the brain causing transient ischemic attacks or strokes. "RGS1, MUC1, KCNA2, TAC1, and SOST were all found to be up-regulated in moyamoya disease." (PMID 40462179, 2025).
non-Hodgkin lymphoma (1 paper, 2023). Distinct from Hodgkin lymphoma both morphologically and biologically, non-Hodgkin lymphoma (NHL) is characterized by the absence of Reed-Sternberg cells, can occur at any age, and usually presents as a localized or generalized lymphadenopathy associated with fever and weight loss. "Also, mTOR shares some signaling pathways with RGS1 as the PI3K/Akt cell cycling pathway, which contributes to the initiation and maintenance of cancer as in Non-Hodgkin lymphomas." (PMID 37437037, 2023).
schizophrenia (1 paper, 2019). A major psychotic disorder characterized by abnormalities in the perception or expression of reality. "The absence of a positive correlation between the medication at the time of blood drawing and RGS1/CCL4 argues against an interpretation that the decreased levels of RGS1/CCL4 could be caused by psychotropic medication of the schizophrenia patients." (PMID 31150013, 2019). "While more studies are needed to characterize the RGS1/CCL4-defined schizophrenia subset and its clinical relevance, our here-proposed approach may prove valuable for changing the diagnostic culture in clinical psychiatry." (PMID 31150013, 2019). "In the hypothesis-guided analysis presented here, however, a causal model, the tgDISC1 rat, was used to define aberrant PBMC signaling that was then rediscovered in a schizophrenia subset converging on the marker combination CCL4/RGS1." (PMID 31150013, 2019). "We propose to apply testing for RGS1/CCL4 in many more cases of chronic mental illness, not limited to schizophrenia, but also to include recurrent affective disorders and neurological brain diseases to delineate its diagnostic accuracy." (PMID 31150013, 2019).
squamous cell carcinoma (1 paper, 2022). A carcinoma arising from squamous epithelial cells. "qRT-PCR and immunohistochemistry tests of the patient tissues confirmed that the expression of RGS1 in cancerous tissue was higher compared to normal tissue, while the expression of squamous cell carcinoma in cancerous tissue was highest." (PMID 35879796, 2022). "Moreover, qRT-PCR confirmed that the expression of RGS1 in the HeLa (adenocarcinoma) and SiHa cell lines (squamous cell carcinoma) was higher than the HcerEpic cell line (normal epithelial cells of the cervix)." (PMID 35879796, 2022). "Further exploration found that the RGS1 protein expression was higher in HPV-E6-positive adenocarcinoma and squamous cell carcinoma tissues than HPV-E6-negative carcinoma tissues." (PMID 35879796, 2022).
Waldenstrom macroglobulinemia (1 paper, 2015). "Plasma cells have a high level of RGS1, and subsequently AKT activation is an important part of MM migration and Waldenstrom macroglobulinemia." (PMID 25897806, 2015).
tumor (37 papers, 2013 to 2026). "Thirdly, further in vivo and in vitro studies were warranted for exploring the underlying mechanism of RGS1 in regulating tumourigenesis and tumour immunity of NSCLC." (PMID 38081176, 2023). "Although the exact mechanism of action remains to be discovered, it is certain that RGS1 promotes tumour cell proliferation, migration and invasion and is associated with poor prognostic survival in diffuse large B-cell lymphoma and multiple myeloma." (PMID 37924113, 2023). "Existing research has suggested that RGS1 may be correlated with T cells, whereas the regulation of RGS1 with tumor-associated macrophages has been rarely reported." (PMID 37735297, 2024). "Additionally, the TIMER database also suggested that RGS1 was positively associated with several tumour‐infiltrating immune cells, including B cells, CD8+ T‐cells, CD4+ T‐cells, macrophages, neutrophils and dendritic cells." (PMID 38081176, 2023). "For instance, RGS1 has been identified as a novel marker and promoter of CD8+ T cell exhaustion, while RGS2 is closely linked to the distribution and function of tumor‐infiltrating immune cells within the CRC tumor microenvironment." (PMID 40891683, 2025). "RGS1 is a germinal center chemokine regulator for B-cells, and it is expressed at higher levels in tumor-infiltrating B-cells than in circulating B-cells." (PMID 39409999, 2024). "RGS1 is critical to immune cells’ activation and differentiation, and the correlation between tumor-infiltrating immune cells (TIICs) and RGS1 overexpression within the ccRCC microenvironment was investigated in depth." (PMID 37735297, 2024). "Using the TCGA database and GO analysis to describe the expression of RGS1 in a range of tumors, it was found that ccRCC had a much higher level of RGS1 expression than other tumor types." (PMID 37735297, 2024). "The difference in RGS1 expression in the TCGA was verified using 530 tumor samples and 72 normal samples, and the result indicated that much more RGS1 was expressed in the tumor than within the normal group, consistent with the result in the paired analysis." (PMID 37735297, 2024). "GO analysis and the TCGA database was used to describe the expression of RGS1 in various tumor types, and the result indicated that RGS1 was significantly expressed in ccRCC." (PMID 37735297, 2024). "Deletion of the RGS1 SE significantly decreased the tumour burden and prolonged survival in subcutaneous experiments while also reducing tumour nodules in the liver of mice subjected to the orthotopic experiments." (PMID 38514625, 2024). "Since the regulating role of RGS1 on the tumour immune microenvironment has been recognised recently, this study also investigated this issue through the TIMER database, which showed that RGS1 was negatively correlated with cancer purity." (PMID 38081176, 2023). "From the clinical aspect, another study indicates that the aberrant expression of tumour RGS1 in several cancers (including liver hepatocellular carcinoma, pancreatic cancer and thymoma) is related to poor prognosis." (PMID 38081176, 2023). "RGS1 serves as a negative regulator to inhibit the chemotaxis of cytotoxic T lymphocytes and TH1 cells toward tumor-associated chemokines." (PMID 37234685, 2023). "The subpopulations with double-positive expression of BTG1 and RGS1 were significantly enriched in tumor lesions." (PMID 37333982, 2023). "Effects of RGS1 silence on tumor cell proliferation in vitro and tumor growth in vivo were also evaluated." (PMID 37529094, 2022). "The tumor weight in the sh-RGS1 group was only 37% and 43.6% of the tumor weight in the sh-NC group." (PMID 35879796, 2022). "Inhibition of RGS1 in a mouse tumor model promoted the infiltration of effector T cells, further illustrating the effect of RGS1 on lymphocyte migration." (PMID 36225936, 2022). "Totally, RGS1 gene-silenced NCIN87-DR cell immunization obviously inhibited tumor growth of Xenograft tumor mice." (PMID 37529094, 2022).
tumor (continued). "The RGS1 gene-silenced NCIN87-DR cell immunization obviously decreased the tumor size of Xenograft mice compared to that of solely NCIN87-DR cell immunized Xenograft mice (p < 0.05)." (PMID 37529094, 2022). "In tumorigenesis experiments in nude mice, we found that tumor growth was slower in the sh-RGS1 group." (PMID 35879796, 2022). "A previous study reported that RGS1 plays an important role in tumor cell response and proved the possibility of its involvement in tumor cell immunity." (PMID 37529094, 2022). "Consistently, protein expression of PEG10 and RGS1 showed significantly high expression in tumor tissue than in the normal tissue." (PMID 35677557, 2022). "Type II interferon (IFN) and STAT1 signaling increase RGS1 expression and prevent T cell transport to tumor by inhibiting calcium influx and inactivating kinases ERK and AKT." (PMID 35879796, 2022). "We found that although RGS1 is considered to be a tumor promoter, the level of RGS1 expression was low in late FIGO stage, late T stage and M1 stage." (PMID 35879796, 2022). "We observed higher expression of Arg1, Il1a, and Rgs1 in macrophages from scaffolds compared with those from the primary tumor." (PMID 33782087, 2021). "In order to evaluate the role of RGS1 in tumorigenesis, we analyzed the expression levels of RGS1 between tumor and normal tissues in the TCGA database." (PMID 34956194, 2021). "RGS1 protein highly expressed in tumor tissues was also verified in the immunohistochemistry (IHC) experiment." (PMID 34956194, 2021). "Although expression of CYR61, DUSP1 and RGS1 was detected, only RGS1 showed significant up-regulation in tumor tissue across all time points of ischemia." (PMID 26222051, 2015). "In tumor tissue samples, RGS1 expression level increased over time and was stable 20 minutes post-resection." (PMID 26222051, 2015). "Furthermore, in all patients observed, compared to the normal group, the tumor group had increased levels of RGS1 expression." (PMID 37735297, 2024). "A comprehensive investigation has shown the existence of a hitherto unidentified subgroup of TAMs known as RGS1 + TAMs, which has been found to have a strong correlation with the efficacy of immunotherapy and the occurrence of tumor metastasis in LUAD patients." (PMID 38653742, 2024). "We also further explored and studied the expression and function of RGS1 in TME, investigated how RGS1 affected tumor growth, migration, apoptosis, and other traits, and initially explored the signaling pathways and mechanisms that RGS1 may affect." (PMID 37735297, 2024). "Other genes: BTG1, CD24, KRT19, RAC2 and RGS1 were significantly upregulated in tumour samples." (PMID 39098994, 2024). "Moreover, plentiful evidences reveal that RGS1 exerts an essential role in regulating tumour immunity, which further promotes tumourigenesis, tumour progression and drug resistance." (PMID 38081176, 2023). "Elevated blood RGS1 was related to lymph node metastasis (P = 0.001), higher tumour‐nodes‐metastasis stage (P = 0.004), neoadjuvant chemotherapy administration (P = 0.044), shortened disease‐free survival (DFS) (P = 0.008) and overall survival (OS) (P = 0.013) in NSCLC patients." (PMID 38081176, 2023). "Thus, RGS1 gene-silenced NCIN87-DR cell immunization inhibited tumor growth through downregulating Ki67 expression in tumor tissues of Xenograft tumor mice." (PMID 37529094, 2022). "The immunohistochemical assay results indicated that RGS1 gene-silenced NCIN87-DR cell immunization could downregulate Ki67 expression in tumor tissues of Xenograft tumor mice." (PMID 37529094, 2022). "RGS1 gene knock-down vector (pLVshshRGS1) and Xenograft tumor mouse model was generated." (PMID 37529094, 2022). "RGS1 gene-silenced NCIN87-DR cell immunization could also strengthen inhibitive effect of T-mab on tumor growth." (PMID 37529094, 2022).